MTOR (mechanistic target of rapamycin kinase)
Diseases named in the same sentence as MTOR in open-access papers (continued):
Sharing a sentence is not in itself a finding about the gene and the disease.
PEComas (continued). "PEComas are related to the genetic alterations of tuberous sclerosis complex (TSC), an autosomal dominant genetic disease associated with losses of TSC1 (9q34) or TSC2 (16p13.3) genes, which seem to have a role in the regulation of the Rheb/mTOR/p70S6K pathway." (PMID 24965209, 2014). "PEComas are most commonly found in females and often show either TSC1 or TSC2 alterations, which result in the activation of the mTOR pathway, or TFE3 fusions." (PMID 37041531, 2023). "Both mTOR inhibitors and VEGFR inhibitors exhibited clinical utility in treating malignant PEComas, but the combination of these two regimens has rarely been reported." (PMID 35965503, 2022). "Across histologies, mTOR-inhibition is known to be active in PEComas, often harbouring genetic aberrations and activation of the TSC1/2–mTOR signalling pathway." (PMID 28571564, 2017). "Based on the fact that PEComas share activation of the mTOR pathway with LAM and angiomyolipoma in many instances, we treated our patient with everolimus, an inhibitor of mTOR." (PMID 22943457, 2012). "mTOR inhibitors, including Sirolimus, Everolimus, and Temsirolimus, have been used in the treatment of PEComas, but the results are not very promising." (PMID 39220642, 2024). "Indeed, mTOR inhibitors have recently demonstrated significant efficacy and have been FDA-approved as a treatment for malignant PEComas." (PMID 37041531, 2023). "This trial investigated nab-sirolimus, a nanoparticle-albumin bound formulation of sirolimus in patients with metastatic, unresectable PEComas of any anatomic site, who had not previously received an mTOR inhibitor." (PMID 37504306, 2023). "This mTOR pathway is reported to be inappropriately up regulated not only in TSC-associated AML, but also in sporadic angiomyolipoma or PEComas." (PMID 22943457, 2012). "However, there is a lack of clinical studies evaluating mTOR inhibitors in PEComas with or without TFE3 translocation." (PMID 40989692, 2025). "However, the dysregulation of the mTOR pathway has also been observed in sporadic hepatic PEComas without TSC evidence." (PMID 40723161, 2025). "However, no studies have been conducted to compare the response to mTOR inhibitors in PEComas with and without TFE3 translocation." (PMID 39026968, 2024). "However, there is no study assessing the response to mTOR inhibitors for PEComas with and without TFE3 translocation." (PMID 34680376, 2021). "The response of TFE3 gene-rearranged PEComas to mTOR inhibitors is not well defined, and." (PMID 32685651, 2020).
squamous cell carcinoma (61 papers, 2007 to 2026). A carcinoma arising from squamous epithelial cells. "Specifically, deregulation of the TGF-beta, VEGF, mTOR, Wnt, Hedgehog and insulin signaling pathways has been found to be associated with aggressive disease in squamous cell carcinomas." (PMID 23950933, 2013). "Further investigation beyond squamous cell cancers will be required to test whether FA pathway loss leads to mTOR addiction under limited amino acid/nutrient supplies in other tumor types." (PMID 40805278, 2025). "The upregulation of the mTOR and AKT was also demonstrated in NSCLC with up to 90% of phosphorylated mTOR (p-mTOR) in 90% of patients with adenocarcinoma, 60% of patients with large cell carcinoma, and 40% of patients with squamous cell carcinoma." (PMID 38396649, 2024). "For example, the PI3K/Akt/mTOR pathway is upregulated in more than 90% of H&N squamous cell carcinomas, resulting in an increased resistance to chemotherapy and radiotherapy and cancer progression." (PMID 35992863, 2022). "In line with our observation, previous studies have shown that PER1 is able to inhibit Akt/mTOR signalling, although in squamous cell carcinoma, and plays a role in the regulation of cytokine expression, such as IFNG, in NK cells." (PMID 35143696, 2022). "Activating mutations in PIK3CA result in the activation of the phosphoinositide 3-kinases/protein kinase B/mTOR pathway, which is commonly seen in other organs’ squamous cell carcinomas." (PMID 33482222, 2021). "Examples of these pathways include fatty acid biosynthesis and metabolism, cell proliferation and invasiveness of squamous cell carcinomas of the head and neck, the Arf1 and mTOR/P70S6K pathways." (PMID 27049860, 2016). "Luteolin induced autophagy in squamous cell carcinoma cells and also inhibited the activation of the Akt-mTOR-p70S6K pathway." (PMID 26338671, 2015). "Similarly, preclinical combination studies of alpelisib and cetuximab inhibited EGFR phosphorylation, resulting in inhibition of mTOR activation and subsequent cell death in squamous cell carcinoma cells and tumors." (PMID 40161411, 2025). "In the present study, it was found that the positive expression rate of mTOR in the BD group and AK group was higher than that in the normal skin group, indicating that mTOR may be involved in the occurrence of squamous cell carcinoma." (PMID 34874800, 2021). "Therefore, we believe that here we provide evidence for the high expression of CHRNB4 caused by tobacco and alcohol, thereby inducing the formation of squamous cell carcinoma through cancer-related pathways such as mTOR." (PMID 33304845, 2020). "Interestingly, the recent study showed that the PI3K pathway was critical for epidermal homeostasis and the activation of PI3K-dependent signalling pathway, in particular, the PI3K-Akt-mTOR pathway, played a key role in squamous cell carcinoma." (PMID 30902093, 2019). "Interestingly, activation of ATF6α-Rheb-mTOR pathway promotes survival of quiescent squamous carcinoma cells and subsequent adaptation to chemotherapy." (PMID 28835710, 2017). "Combined analysis of proteome and interactome data highlighted key proteins and suggested that adenocarcinoma might be more prone to PI3K/Akt/mTOR and topoisomerase IIα inhibitors, and squamous carcinoma to Ck2 inhibitors." (PMID 27814385, 2016). "The siRNAs against mTOR, Raptor and Rictor were employed to reduce the expression of both mTORC1 (mTOR and Raptor) and mTORC2 (mTOR and Rictor) in Cal27 cells, an established cell line derived from the poorly differentiated squamous cell carcinoma of the tongue." (PMID 26895469, 2016).
squamous cell carcinoma (continued). "Thus, further evaluation of PI3K/AKT/mTOR pathway targeted therapy is warranted, especially in metastatic or recurrent squamous cell carcinoma." (PMID 25426553, 2014). "Whether the PI3K/mTOR/S6 and Src pathways are more critical in adenocarcinoma than in squamous cell carcinoma or whether this finding was due to smaller numbers of squamous cell carcinoma samples in the study is not clear." (PMID 22348039, 2012). "Notably, this mTOR-Wnt axis may have broader relevance: our prior work identified mTOR-mediated control of FGF10 in squamous carcinoma, suggesting a conserved paradigm where mTOR calibrates morphogen signaling across biological contexts." (PMID 40060475, 2025). "Since the mTOR pathway is upregulated in NSCLC, the concentration of p-mTOR increases by up to 90% in NSCLC patients with adenocarcinoma, and up to 60% and 40% in NSCLC patients with large cell carcinoma and squamous cell carcinoma (SCC), respectively." (PMID 39349424, 2024). "Using two CCR7(+) lymph node metastasis-derived squamous cell carcinoma cell lines, autologous CCL19 induced the phosphorylation of mammalian target of rapamycin (mTOR)." (PMID 35203305, 2022). "Reports suggest that, during hypoxia or energy stress in the head and/or neck, squamous cell carcinoma (HNSCC) cells, regulated in developmentand DNA damage responses -1 (Redd1) inhibits mTOR signalling by upregulating AMPK." (PMID 29996471, 2018). "In the case of squamous cell carcinoma (SCC), p-mTOR showed different staining patterns depending on the tumor sites." (PMID 28831205, 2017). "HIF1A and MMP3: Previous studies have highlighted their roles in promoting invasion and metastasis in other squamous cell carcinomas or skin tumors, this study for the first time links both genes to the PI3K/AKT/mTOR signalling pathway and validates their expression changes via qPCR." (PMID 41438693, 2026). "Increased mTOR expression and phosphorylation were observed in close to 90% of NSCLC patients with adenocarcinoma, while 60% of patients had large cell carcinoma and 40% of patients had squamous cell carcinoma." (PMID 34178653, 2021). "A recent study using human squamous carcinoma cell lines has shown that luteolin ameliorates cancer metastasis by reducing the expression and activity of ribosomal protein S19 and inhibiting the AKT/mTOR/c-Myc signaling pathway." (PMID 32224968, 2020). "In squamous cell carcinoma (SCC) cells Axl has been shown to dimerize with EGFR and promote ligand independent phosphorylation of EGFR, leading to increased activation of phospholipase Cγ (PLC γ) and protein kinase C ζ (PKCζ), as well as mTOR." (PMID 27611946, 2017). "Upregulation of the mTOR pathway has also been reported in a large number of NSCLC tumors, with increased p-mTOR expression in up to 90% of patients with adenocarcinoma, 60% of patients with large cell carcinoma, and 40% of patients with squamous cell carcinoma." (PMID 32927648, 2020). "On the other hand, ATF6α prolongs survival of dormant tumor cells, but not proliferative squamous carcinoma cells, through transactivation of the Ras homolog enriched in brain (Rheb; a critical activator of the mammalian target of rapamycin [mTOR]) and thus activation of mTOR signaling." (PMID 28860159, 2017). "Two molecules (COX2 and S6) were not significantly different when adenocarcinoma and squamous cell carcinoma were analyzed separately, while PI3K-p85, Src, and mTOR remained significantly different between normal and tumor tissues in adenocarcinoma but not in squamous cell carcinoma." (PMID 22348039, 2012).
Autoimmunity (60 papers, 2008 to 2025). The occurrence of an immune reaction against the organism's own cells or tissues. "An imbalance in the PI3K/AKT/mTOR pathway favors EF B cell development, impairs selection processes, and predisposes individuals to autoimmunity." (PMID 39917832, 2025). "Dysregulated PI3K/AKT/mTOR signaling is implicated in the initiation and modulation of autoimmunity and inflammation." (PMID 39872540, 2024). "Dysregulation of the mTOR pathway is implicated in several diseases, including autoimmune disorders, cancer, neurological conditions, and metabolic disorders." (PMID 38993452, 2024). "Overactivation of the mTOR pathway in T cells is also associated with autoimmune disorders such as systemic lupus erythematosus." (PMID 37628917, 2023). "As mTORC1 is essential for lymphocyte activation and function, the dysregulation of mTOR activity is associated with several lymphocyte defects leading to pathologies such as malignancies and autoimmune disorders." (PMID 37628917, 2023). "mTORC1 signaling is constitutively active in Treg cells, and disruption of mTOR protein as well as unrestrained mTOR hyper-activation, both have been shown to cause autoimmunity by impairing Foxp3 expression and Treg functions." (PMID 30906299, 2019). "Studies in animal models have suggested that reduced PI3K/AKT/mTOR/S6K signaling (hypoactivation) can lead to immune deficiency, whereas uncontrolled PI3K/AKT/mTOR/S6K signaling (hyperactivation) is associated with autoimmunity and hematological malignancies." (PMID 29867948, 2018). "Because of these critical biological effects, dysfunctional mTOR signaling is also linked to autoimmunity, obesity, and cancer, among other conditions." (PMID 25653651, 2014). "Patients with TSC might have a higher risk of developing SLE because both share a common mTOR signaling pathway and trigger autoimmunity." (PMID 38993452, 2024). "In summary, the concurrent deficiencies in TGF-β, mTOR and HK-II in juvenile SHRs may lead to impaired immune functions, including memory, tolerance, and the risk of autoimmunity." (PMID 39513878, 2024). "In SMCR8 and in C9ORF72 deficient mice, promoting autophagy via MTOR inhibition could rescue the autoimmunity phenotype, definitely establishing a causative link between the cellular function of C9ORF72 and immune dysfunction." (PMID 37138765, 2023). "Increasing body of data suggests that alterations in the PI3K/AKT/mTOR pathway may result in an enhanced susceptibility to autoimmunity." (PMID 29492193, 2018). "Increasing body of data suggests that alterations in the PI3K/Akt/mTOR pathway may result in enhanced susceptibility to autoimmunity." (PMID 29492193, 2018). "mTOR has been implicated in the pathogenesis of autoimmune disorders, like SLE17." (PMID 28811467, 2017). "mTOR controls proteins synthesis required for cell proliferation and is implicated in a variety of human disorders, including cancer, cardiovascular disease, autoimmunity, metabolic disorders and inherited disease." (PMID 27258250, 2016). "One way that amino acids can modulate the immune response through mechanistic target of rapamycin (mTOR), a paramount regulator and sensor of nutrient status, intracellular metabolism, oxidative stress, and immune response that is implicated in the development of autoimmunity." (PMID 37283765, 2023). "This expands the clinical understanding of HA20 and suggests potential therapeutic avenues targeting the mTOR pathway for HA20-related autoimmune conditions." (PMID 40719110, 2025). "Historically, sirolimus significantly reduced autoantibodies in MRL/lpr−/− mice, further supporting PI3K/mTOR inhibition to improve autoimmunity." (PMID 41608120, 2025). "This suggests the involvement of A20 in derailment of the mTOR pathway, thereby providing a novel insight into the emergence of autoimmunity in HA20." (PMID 40719110, 2025).
Autoimmunity (continued). "Activation of the mechanistic target of rapamycin (mTOR) is important in the metabolic function of proinflammatory T cells in autoimmunity." (PMID 38519468, 2024). "Here the authors characterise how Rab4A is involved with CD98 and endosome recycling which subsequently affects mTOR activation, autoimmunity and T cell expansion." (PMID 38519468, 2024). "This suggests that Rab4A-mediated mTOR activation is a driver of autoimmunity via expansion of CD4+ over CD8+ T cells in SLE." (PMID 38519468, 2024). "Akt, as the main molecule in the PI3K signaling pathway, has various downstream effects, amongst mammalian target of rapamycin (mTOR) is especially the molecule of interest in the field of autoimmunity." (PMID 37215992, 2023). "mTOR inhibitors have been shown to reduce autoimmunity symptoms in both a mouse model and in humans." (PMID 37628917, 2023). "AKT/mTOR pathway is essential for the proper activation and proliferation of T cells in autoimmunity." (PMID 36008635, 2022). "Collectively, mTOR inhibition blocks T-effector development and function, and can limit related autoimmunity." (PMID 35897651, 2022). "Drugs targeting the PI3K/AKT/mTOR pathway are under investigation for their potential use in autoimmunity as immunosuppressant agents." (PMID 35897651, 2022). "mTOR (mammalian target of rapamycin) is a protein kinase, involved in apoptosis, cell cycle, metabolic disorders and autoimmunity, carcinogenesis, inflammation and autophagy, immunoregulation, and tolerance." (PMID 33414726, 2020). "Stimulation of mTOR, a central issue in autoimmune disorders, also seems to contribute to inflammation in dysfunctional autophagy." (PMID 32124227, 2020). "Here they show how this mTOR signaling orchestrates homeostasis of Treg-cell subsets and prevents fatal autoimmunity." (PMID 29844370, 2018). "The pathways resulting in mTOR deregulation and TH cell dysfunction in autoimmunity are, however, not fully understood." (PMID 28811467, 2017). "mTOR inhibitors, such as rapamycin, are therefore therapeutic through inhibiting aberrant mTOR activity in the treatment of autoimmunity and malignancies." (PMID 26583116, 2015). "In addition to NF-κB and STAT1 activation, we discovered mTOR pathway activation, shedding new light on A20’s function and progression toward autoimmunity." (PMID 40719110, 2025). "This approach could provide valuable insights into how mTOR signaling influences B cell fate decisions and the progression of autoimmunity." (PMID 39917832, 2025). "Both ALPS-FAS and ALPS-CED lead to autoimmunity and improve with use of mTOR inhibitors." (PMID 41026346, 2025). "One of the first reports on the possible role of the mTOR pathway in the regulation of macrophage function in autoimmunity demonstrated the dependence of IL-10 secretion by macrophages cultured with synovial T cells isolated from patients with rheumatoid arthritis on p70 S6 kinase." (PMID 40806725, 2025). "Furthermore, insulin signaling has the potential to mediate macrophage polarization in cancer, while mounting evidence supports the role of mTOR signaling in autoimmunity, which is also essential for the activation and proliferation of T‐cells." (PMID 36282125, 2023). "On the other hand, the use of metformin may affect the development of IBD, probably through its exceptional ability to change the gut microbiota, to maintain or reduce body weight, to modulate autoimmunity, and to inhibit the mTOR pathway." (PMID 37242462, 2023). "The remaining patients may develop severe multiorgan autoimmunity requiring lifelong immunosuppressive treatment with Treg-sparing immunosuppression [mammalian target of rapamycin (mTOR) inhibitors] or targeted soluble CTLA-4-Ig (abatacept, belatacept)." (PMID 36636328, 2022).